RNU7-34P (RNA, U7 small nuclear 34 pseudogene)
Synonyms: U7.34
Gene: Small nuclear RNA gene on chromosome 5 (118,758,211 to 118,758,274, forward strand). Ensembl gene ENSG00000238904.
Homologues: Orthologues: chimpanzee U7 (100% identical), macaque U7 (100% identical), rabbit U7 (80% identical). Paralogues in human: RNU7-7P (88% identical), RNU7-14P (86% identical), RNU7-23P (86% identical), RNU7-1 (84% identical), RNU7-21P (84% identical), RNU7-27P (84% identical), RNU7-2P (84% identical), RNU7-62P (84% identical), RNU7-10P (83% identical), RNU7-172P (83% identical), RNU7-18P (83% identical), RNU7-19P (83% identical), and 143 more.